BRCA1 (BRCA1 DNA repair associated)
Diseases named in the same sentence as BRCA1 in open-access papers (continued):
Sharing a sentence is not in itself a finding about the gene and the disease.
breast cancer (continued). "If the first breast cancer was diagnosed at the age of 50 or later, 25-year cumulative risks were 21.6% for BRCA1, 15.5% for BRCA2, and 12.9% for BRCA1/2 negative families." (PMID 23216834, 2012). "We also transiently overexpressed (for 24-168h) BRCA1/p220 in two none-/low-BRCA1/p220 expressing breast cancer cell lines, MDAMB468 (TN/BL) and SKBR3 (Her2+)." (PMID 22431556, 2012). "In this retrospective study, we show that expression levels of BRE, which encodes a member of the BRCA1 DNA damage repair complex, predicted disease-free survival (DFS) in non-familial breast cancer patients." (PMID 22706632, 2012). "The KRAS variant allele was detected in 17.2% of sporadic breast cancer cases and in 18.2% of all familial cases (10.3% of BRCA carriers - 10.0% of BRCA1 and 11.1% of BRCA2 carriers and in 19.9% of non-BRCA carriers)." (PMID 22436609, 2012). "MDA-MB-231 and BT20 cells are both triple-negative human breast cancer cell lines with functional BRCA1." (PMID 25969759, 2012). "Our data show that the EGFR inhibitor erlotinib was effective in the prevention of EGFR+/ER- breast cancers, but not EGFR-/ER+ breast cancers, in BRCA1-mutant mice." (PMID 21396117, 2011). "On the other hand, the proportion of detected mutations in BRCA1 and BRCA2 genes fell to 36% when we investigated the subgroup of families with at least two ovarian cancers and no breast cancer in their family history (Subgroup - only O)." (PMID 21232165, 2011). "Indications for skin-sparing mastectomy are BRCA1/2 mutation, intraepithelial neoplasia (DIN or LIN), particularly when the lesion is extensive, multicentric or recurrent, and early-stage breast cancer for which breast-conserving therapy is not suitable." (PMID 22312537, 2011). "Reconstitution of wild-type BRCA1 into BRCA1-negative HCC1937 breast cancer cells resulted in a 20-fold increase in cisplatin resistance and, in contrast, a 1000- to 10 000-fold increase in sensitivity to paclitaxel and vinorelbine." (PMID 21157449, 2011). "Our previous analysis of the BRCA1 promoter had pointed to the ets transcription factor GA Binding Protein (GABP) and its RIBS binding element as key regulators of BRCA1 expression, particularly as it relates to its decrease in sporadic breast cancers." (PMID 21609478, 2011). "The syndromes most strongly associated with both cancers are the BRCA1 or BRCA2 mutation syndromes, but these do not account for most breast cancers that arise in the general population." (PMID 21487409, 2011). "Absent or reduced BRCA1 expression was seen more in high-grade breast carcinoma compared to better-differentiated tumours." (PMID 23508738, 2011). "We observed differences in the frequency of common genetic variants of the BRCA1 and BRCA2 and their haplotypes between early-onset breast cancer cases who did and did not carry deleterious mutations in these genes." (PMID 20807450, 2010). "We were able to accurately classify BRCA1 and BRCA2 samples, and our results supported other reported findings that suggested familial breast cancer patients without BRCA1/2 mutations are genetically heterogeneous." (PMID 20174566, 2010). "Comparison of PR and HER2 status between ER+ BRCA1 breast cancers and sporadic controls was not possible due to the unavailability of data for many of the controls." (PMID 20149218, 2010). "Twenty-nine of the 138 patients with ER+ sporadic breast cancers (21%) had undergone genetic testing at BIDMC and none was found to have a BRCA1 or BRCA2 mutation." (PMID 20149218, 2010).
breast cancer (continued). "We used DNA–damaging agents to disturb gene expression profiles of cell-lines derived from blood of patients, and we compared patterns from women with BRCA1 and BRCA2 mutations to women familial breast cancer families without such mutations." (PMID 20174566, 2010). "A similar study used short-term fibroblast cultures from skin biopsies from 10 BRCA1 and 10 BRCA2 mutation carriers and 10 individuals who had previously had breast cancer but were unlikely to contain BRCA1/2 mutations." (PMID 20174566, 2010). "However, the conflicting evidences on a communication between XIST and BRCA1 prompted us to further investigate on this issue and on XIST behaviour in breast cancer cells." (PMID 19440381, 2009). "This evidence indicates that defects in heterochromatin compartment are a trait of breast cancer cells, irrespective of BRCA1 status." (PMID 19440381, 2009). "For the majority of tested women, a BRCA1 or BRCA2 mutation is not found, and counselling regarding breast cancer risk is based on the review of the pedigree." (PMID 19088722, 2009). "We therefore performed a study of hypoxic factors in BRCA1, BRCA2 and BRCAX breast cancers." (PMID 19724277, 2009). "Otherwise, we reported that in breast cancer cells, in spite of the presence of two or more X chromosomes, none of them is functionally inactivated, irrespective of BRCA1 status, and all the X chromosomes are copies of native active X (Xa)." (PMID 19440381, 2009). "DEAR1 loss of expression did not correlate with BRCA1 or BRCA2 mutation, but rather, loss of expression correlated with a strong family history of breast cancer in this young cohort (r = −0.24, p = 0.0139)." (PMID 19536326, 2009). "Indeed, homozygous Brca1Tr mouse mutants that express BRCA1-Δ11 are viable on a BALB/c genetic background, but develop various tumours including mammary carcinomas after long latency." (PMID 19904273, 2009). "A recently study show that absence of BRCA1 expression is a predictor of shorter TTP (time to progression) in advanced breast cancer patients treated with taxane-based therapy." (PMID 18402708, 2008). "In terms of the potential for targeting this activity for breast cancer therapy, tumor suppressors such as BRCA1 are not ideal targets for therapy because small molecule activators can be more difficult to produce than small molecule inhibitors." (PMID 19007432, 2008). "Therefore, we assessed BRCA1 mRNA expression in 61 TNBC and 60 consecutive luminal subtype breast cancers." (PMID 18950515, 2008). "In spite of advances in detection and clinical management for patients with familiar BRCA1 mutant breast cancer, there has been no significant improvement in therapies and overall survival for these patients." (PMID 18394172, 2008). "RNAPII P-CTD cleavage was observed in UV-irradiated BRCA1 (+/+) cells (MCF7) but not in BRCA1 (−/−) breast cancer cells following proteasome inhibition." (PMID 18197258, 2008). "We believe it will be important to examine individuals with early onset or multifocal breast cancer for BRCA1 methylation lacking a strong family history." (PMID 18269736, 2008). "In this study, we demonstrate the presence of BRCA1 promoter methylation in normal non-epithelial tissues of patients that developed breast cancer." (PMID 18269736, 2008). "In this study, we evaluated expression of basal CKs among tumours from BRCA1, BRCA2 and non-BRCA1/BRCA2 families (families with several breast cancer patients without BRCA1 or BRCA2 mutations), and sporadic breast cancer patients." (PMID 18275599, 2008).
breast cancer (continued). "In this study we compared LCL gene expression signatures of breast cancer cases carrying pathogenic mutations in BRCA1 or BRCA2, to familial breast cancer cases with no known BRCA1/2 mutations (BRCAX)." (PMID 18497862, 2008). "In the current study, we examined a panel of 25 BRCA1/2 negative, affected French Canadian women alongside 25 healthy controls, to investigate the impact of CHEK2 variants on breast cancer susceptibility in the French Canadian population." (PMID 18706089, 2008). "We further show that UV-irradiation results in a proteasome dependent accumulation of the P-CTD cleavage product in yeast and human breast cancer cells wild type for BRCA1 but not in a BRCA1 mutant cell line." (PMID 18197258, 2008). "411/839 (49%) BRCA1 carriers and 355/603 (59%) BRCA2 carriers had developed breast cancer." (PMID 18513387, 2008). "Where the family history is not strong, the chances of a major gene mutation (BRCA1 or BRCA2) being present are small and so too is the risk of very early-onset breast cancer." (PMID 18283300, 2008). "Cell lines derived from individual Brca1 mouse mammary tumors had distinct and non-overlapping populations of putative cancer stem cell markers CD44+/CD24- and CD133+." (PMID 18241344, 2008). "We report the frequencies of these alleles in BRCA1 and BRCA2 mutation-positive cases, and compare these frequencies with mutation-negative familial breast cancer cases, as well as female French Canadian controls with no personal history of cancer." (PMID 18402691, 2008). "According to the Breast Cancer Information Core (BIC) database, the majority of germline alterations identified in BRCA1 and BRCA2 is unique (57% and 63%, respectively); the remaining ones are recurrent founder mutations which have been described in different ethnic groups and populations." (PMID 17640379, 2007). "Tumor-suppressor genes with aberrant methylation in breast cancers include ARHI, RASSF1A, HIN-1, the retinoic acid receptor II gene (RARβ2), hMLH1, 14-3-3 σ, RIZ1, p16, the E-cadherin gene, PTEN, and BRCA1." (PMID 17764565, 2007). "We performed mutation analysis of 38 BRCA1/2 mutation-negative breast cancer families with male breast cancer, prostate cancer, and/or haplotype sharing around BCoR-L1 to determine whether there is a role for BCoR-L1 as a high-risk breast cancer predisposition gene." (PMID 17697391, 2007). "For example high grade, ER, PR and HER2 negative tumours are significantly more frequent in BRCA1 gene carriers than in breast cancers in none gene carriers." (PMID 17697367, 2007). "We examined the mutation frequency of BRCA1, BRCA2, CHEK2 and ATM in women who had developed a second primary breast tumour at least 1 year after a first breast cancer diagnosed before the age of 50 years, with or without RT for their first breast cancer." (PMID 17428320, 2007). "This is intriguing in that most BRCA1 mutant breast cancers are hormone receptor negative and here we showed that BRCA1 hypermethylation is also associated with hormone receptors negativity." (PMID 17270052, 2007). "Rare BRCA1/2 sequence alterations were observed in 15 out of 105 (14.2%) early-onset cases without family history and 11.7% (4/34) breast cancer cases with family history." (PMID 17018160, 2006). "One explanation could be that, compared to sporadic cases, BRCA1/BRCA2-related breast cancers, as well as breast cancers diagnosed in the context of a strong family history, are less susceptible to be detected by mammography screening." (PMID 16404417, 2006). "In these studies, BRCA1 status was a strong predictor of breast cancer survival only among women who did not receive chemotherapy, while among women who received chemotherapy it was not." (PMID 16404417, 2006). "Marco Pierotti (Milan, Italy) reviewed his experience with microarray studies aimed at the molecular classification of BRCAX, familial breast cancers that do not involve the BRCA1 and BRCA2 genes." (PMID 16464241, 2006).
breast cancer (continued). "In other words, women with an altered BRCA1 or BRCA2 gene are 3 to 7 times more likely to develop breast cancer than women without alterations in those genes, with very high relative risks for early disease onset (before age 40) of about 30-fold." (PMID 17018160, 2006). "The BACH1 gene was screened for germ line alterations among probands from 43 Finnish BRCA1/2 negative breast cancer families." (PMID 16430786, 2006). "Carrying a BRCA1 or BRCA2 mutation is not a risk factor for spontaneous abortions and spontaneous abortions do not appear to influence the risk of breast cancer in carriers of BRCA1 or BRCA2 mutations." (PMID 16563180, 2006). "The TMA contained cores from 20 BRCA1, 14 BRCA2 and 59 sporadic age-matched breast carcinomas." (PMID 16595007, 2006). "For instance, BRCA1 breast cancers are most often ER and PR negative, but BRCA2 cancers more often tend to be positive for these receptors." (PMID 15714204, 2005). "However, BRCA-1 and BRCA-2 mutations appear to be associated with a reduction in efficiency of DNA repair, which suggests that there may be an interaction between these two risk factors, at least for this subgroup of women with a family history of breast cancer." (PMID 16136033, 2005). "This trend is not consistent with the study of The Breast Cancer Linkage Consortium (BCLC) reporting an increased ovarian to breast cancer ratio in the central region of BRCA1 due to a lower breast cancer risk." (PMID 15026808, 2004). "The tendency for a significant proportion of gene carriers (particularly BRCA1) to have oestrogen-receptor-negative breast cancer suggests limited efficacy of SERMS in the treatment of breast cancer in this group." (PMID 15505627, 2004). "An increased frequency of CHEK2*1100delC was found among breast carcinoma families without BRCA1 or BRCA2 mutations, associated with an approximately two-fold increase of breast cancer risk in female carriers." (PMID 14970869, 2004). "The effect of resveratrol on BRCA1 and BRCA2 mRNA in human breast cancer cell lines could be explained by its different properties." (PMID 12838319, 2003). "In contrast to normal breast epithelial cells, BRCA1 mRNA levels in tumours appeared to be downregulated by methylation, while BRCA2 showed significant overexpression in sporadic breast cancers." (PMID 12838319, 2003). "In nude mice, MCF-7 breast cancer tumour growth is inhibited by transfection with wild-type but not mutant BRCA1." (PMID 12698194, 2003). "Among the breast cancer cases, the age-adjusted mean score was slightly lower for BRCA1/2 carriers than noncarriers (mean difference 3.77, P=0.014)." (PMID 12592359, 2003). "Mutant BRCA1 transfection does not inhibit breast cancer cell growth; ovarian cancer cell growth is unaffected by 5′ but inhibited by 3′ BRCA1 mutations." (PMID 12698194, 2003). "Here, we studied the effects of resveratrol on the expression of BRCA1 and BRCA2 in human breast cancer cell lines at the transcription level using quantitative real-time reverse transcription (RT)–PCR, and at the translation level by perfusion chromatography of the proteins." (PMID 12838319, 2003). "It is clear from studies by the Breast Cancer Linkage Consortium that BRCA1 and BRCA2 mutations do not account for all multi-case breast cancer families." (PMID 11875732, 2002). "We genotyped 188 BRCA1/2 carriers (122 affected and 66 unaffected with breast cancer), 158 of them of Ashkenazi origin, 166 BC cases without BRCA1/2 mutations and 156 Ashkenazi control individuals aged over 56 for the AR CAG and GGC repeats." (PMID 11437399, 2001).
breast cancer (continued). "We also demonstrated two BRCA1 and one BRCA2 mutations in three out of 52 (5.8%) early-onset breast cancer cases without additional family history." (PMID 10952777, 2000). "In sporadic breast cancer, LOH of BRCA1 of BRCA2 does not add decisive prognostic value as stated for familial breast cancer." (PMID 8630282, 1996). "In CHEK2-1100delC carriers, the risk of breast cancer did not change in women also carrying P/LP variants in BRCA1, possibly because CHEK2 and BRCA1 may function in the same biological pathway." (PMID 39858629, 2025). "Its deprivation complemented by the loss of ovarian estrogens may be the primary reason for the recurrence suppression and the reduced breast cancer mortality post-oophorectomy in BRCA1/2 carriers with ER-positive or ER-negative nonmetastatic breast cancer." (PMID 39522613, 2025). "We don’t observe significant differences in the allele frequencies between different regions of Poland, i.e., for BRCA1, PALB2, CHEK2, NBN, RECQL, and also for the GEN1 founder p.Lys645Cysfs*29 variant, neither in breast cancer cases nor in controls (for GEN1 data)." (PMID 40649769, 2025). "This appears to be a new finding compared to an earlier study of GATA3 mutations in familial breast cancer, where GATA3 mutations were found in 22% (7/32) of patients without BRCA1/1 mutations and not identified in patients with germline BRCA1 or BRCA2 mutations (n = 0/23)." (PMID 40439821, 2025). "Furthermore, while our model is a BRCA1-mutant TNBC, the citENO1 vaccine could potentially be applicable to other breast cancer subtypes." (PMID 40573960, 2025). "Germline testing of the BRCA1 and BRCA2 genes (BRCA) has been well-established for more than two decades for women with invasive breast cancer (BC)." (PMID 39876688, 2025). "We showed that there is a coordinated behavior between BRCA1 and BRCA2 in breast cancer, reflected in their expression patterns, and also that the BRCAness profile could be important in different tumor types and should be taken into consideration in patient management." (PMID 41373491, 2025). "Second primary breast cancers (2.12 v 1.42 events per 100 person-year) and nonbreast primary malignancies (0.70 v 0.45 events per 100 person-year) were more frequent among BRCA1 than BRCA2 carriers, whereas distant recurrences were less frequent (1.51 v 2.06 events per 100 person-year)." (PMID 39993249, 2025). "Interestingly, BRCA1 and BRCA2 are often coinherited in ovarian and breast cancers." (PMID 39985003, 2025). "BRCA1-associated breast cancers tended to be earlier onset at diagnosis (p = 0.003), and when invasive, were higher grade (p < 0.001), node-negative (p = 0.01), and more commonly TNBC (%TNBC: 69.4% BRCA1 vs. 24.7% BRCA2 vs. 31.6% PALB2; p < 0.001)." (PMID 40275390, 2025).